CXCL8 (C-X-C motif chemokine ligand 8)
Diseases named in the same sentence as CXCL8 in open-access papers (continued):
Sharing a sentence is not in itself a finding about the gene and the disease.
cancer (continued). "IL-8/CXCL8 was the first described angiogenic, mitogenic, and motogenic chemokine in various cancer models and is the prototype of ELR+ CXC chemokines." (PMID 20540789, 2010). "By mRNA profiling, we found that these cytokines, including CCL2, GM-CSF, and CXCL8, might be important downstream targets of N4BP1 in establishing the cancer microenvironment." (PMID 41513619, 2026). "Additionally, the interactions between chemokines, including CXCL1, CXCL8, and CCL2, and ACKR1, expressed by endothelial cells, were notably greater in MHC-II+ cancer cells than in MHC-II− cancer cells." (PMID 41281745, 2025). "Results showed no modifications of CXCL8 mRNA in all thyroid cell types (both normal and cancer cell lines) treated with AZD5069 (Student’s t-test NS)." (PMID 38900374, 2025). "Among the identified prognostic genes, TIMP1, CXCL8, and MGP have been reported in various cancers." (PMID 40299331, 2025). "Specific chemokines, including CCL5, CXCL8/IL‐8, and CCL2, can attract macrophages and leukocytes to the cancer site, where they might produce other angiogenic factors and VEGF that promote the formation of new blood vessels." (PMID 40969301, 2025). "In glioblastoma, CXCL8 supports the M2-like phenotype in TAMs through the CXCR2-JAK2/STAT3 axis, further highlighting the role of these signaling pathways in influencing macrophage behavior and impacting disease outcomes in different types of cancers." (PMID 40055311, 2025). "While CXCL8 mRNA expression levels were not affected by AZD5069 in any of the cancer cell types, some specific patterns of inhibition were observed for the CXCL8 protein." (PMID 38900374, 2025). "It was found that the core targets such as PTGS2, CXCL8, TGFB1, and STAT3 were mainly enriched in the pathways related to cancer and several inflammatory factors, and that tretinoin and PTGS2 as well as tretinoin and PTGS2, CXCL8, and STAT3 had strong binding activities." (PMID 39224778, 2024). "In the present study, although the extent of senescence elicited by DNA‐damaging agents and CDK4/6i was similar, CDK4/6i‐induced senescent cancer cells showed significantly lower expression of well‐known pro‐inflammatory SASP such as IL‐6, CXCL1, CXCL8, and TGF‐β." (PMID 37854019, 2024). "CXCL-8 has been known to promote tumoral angiogenesis, and reducing the adverse effects of CXCL-8 signaling may be beneficial in cancer treatment." (PMID 39107287, 2024). "In LA3IK-treated samples, a significant downregulation was observed among genes central in cancer-related inflammation and epithelial-mesenchymal transition (EMT), exemplified by the reduced expression of IL1B, CXCL-8, matrix metalloproteinase 1 (MMP-1), and Zeb-1." (PMID 38272230, 2024). "C-X-C motif chemokine ligand (CXCL8), also known as interleukin-8, is a prototypical CXC family chemokine bearing a glutamic acid-leucine-arginine (ELR) motif that plays key roles in the onset and progression of a range of cancers in humans." (PMID 38807156, 2024). "NK cells with reduced anti-cancer functions in the immunosuppressive lung tumor microenvironment acquire pro-cancer properties and begin to produce and secrete VEGF and CXCR2 ligands such as CXCL1, CXCL2, and CXCL8/IL-8 as well as IL-6, CCL2, matrix metalloproteinases (MMP), and many others." (PMID 38673949, 2024). "Besides, a variety of cancers have heightened levels of neutrophil-specific chemokines such as CXCL6, CXCL8 (IL-8), and CCL3 (MIP-1α)." (PMID 37158964, 2023). "In addition to neutrophil chemoattraction, CXCL8 and other CXC chemokines exhibit wider functions in cancer, directly promoting angiogenesis and cancer cell growth and, notably, reinforcing senescence in a self-amplifying manner." (PMID 37192000, 2023). "In particular, chemokines, including CXCL8, CXCL10, CXCL11, CXCL16, CCL26, and CCL7, as well as chemokine receptors, including CXCR3, CCR2, CCR5, and CCR1, were positively correlated with MRPL13 expression in various cancer types." (PMID 37827692, 2023).
cancer (continued). "Similarly, for the transcriptomics data we found CXCL8 and CD177 to be altered by metformin where the former has been shown to be altered in healthy individuals and cancer patients." (PMID 36593394, 2023). "Interestingly, it has been observed that the levels of Interleukin-8 (IL-8 or CXCL8), which is a pro-inflammatory chemokine, are significantly elevated in different cancers including NSCLC." (PMID 37190124, 2023). "CXCL8, IL1β and PTGS2 are inflammatory mediators that may play an important role in cancer progression by regulating CSC proliferation and self-renewal." (PMID 37138170, 2023). "It is expected to indirectly reduce the probability of peritoneal metastasis by developing a series of drugs targeting CXCL8 or CXCR1/2, or by improving the treatment effect of intraperitoneal chemotherapy on patients, slowing the deterioration of cancer after peritoneal metastasis." (PMID 37377954, 2023). "In the absence of calbindin, cancer cells become the dominant source of CXCL8 as well as of other potent neutrophil chemoattractants in fully transformed tumors." (PMID 37192000, 2023). "Taking into consideration the cancer development process, the following histaminergic genes stood out: GNA15, HRH1-HRH4, MAOA, WASF2, along with inflammation-related genes: AEBP1, CXCL1, CXCL2, CXCL3, CXCL8, SPHK1, and TNFAIP6." (PMID 36902343, 2023). "On the other hand, in transcriptional misregulation in the cancer signaling pathway, only MYCN expression was notably decreased, and the expression of 20 genes, including GADD45A, CXCL8, JMJD1C, RUNX1, and H3C14, was significantly increased in NHEKs upon HPV8 E7 expression." (PMID 35665406, 2022). "Further, the taxane-resistant DUTXR also showed enrichment of biomarkers that play significant roles in cancer progression, development, and maintenance of cancer stemness (CD44) and drug resistance (CDK1, CXCL8), indicating probable involvement of these genes in mCRPC development and progression." (PMID 36497496, 2022). "In our study, we did not perform an analysis of the relationship between CXCL8 concentrations and cancer stage and the presence of metastases." (PMID 36431173, 2022). "The expression of CXCL8 in cancer tissues was significantly higher than that in normal mucosal tissues, which was consistent with our previous results." (PMID 36358719, 2022). "Unfortunately, in the present study, we did not analyze the dependence of CXCL8 levels on the stage of cancer and the presence of metastases; however, in future studies, we plan to perform an equal analysis in the plasma obtained from BC patients." (PMID 36431173, 2022). "However, immunosuppressive chemokines such as CXCL8, CXCL5, CXCL12, CCL2, and CCL22 were generally upregulated across the 13 cancer types." (PMID 34841742, 2022). "IL-8, known as C–X–C motif ligand 8 (CXCL-8), is produced by monocytes, macrophages, neutrophils, lymphocytes, fibroblasts, endothelial cells, and several types of cancer cells." (PMID 35493517, 2022). "The chemokines CXCL8 and CCL20 are modulators of immune cells as well as cancer cells." (PMID 34725321, 2021). "A comparison of serum concentrations of four pro-inflammatory factors (e.g., IL-6, IL-1β, Chemokine (C-X-C Motif) Ligand 8(CXCL8)/IL-8, and TNF-α) in advanced-stage cancer patients showed that IL-1β levels correlated more strongly with clinical characteristics than those of IL-6." (PMID 33557173, 2021). "Similarly, high expression levels of many interleukins including IL6, IL7, CXCL8/IL8, IL11, and IL17A/IL17 are correlated with increased platinum resistance or poor clinical outcome in several types of cancer." (PMID 34645978, 2021). "Interleukin 8 (IL-8 or CXCL8) is a chemoattractant cytokine secreted from various cells such as leukocytes, endothelial cells, fibroblasts and malignant tumor cells under certain environmental stressors and takes part in malignant cell migration, proliferation and angiogenesis." (PMID 34066014, 2021).
cancer (continued). "In other types of cancer, the effect of HIF-1 may differ—for example, in colon cancer cells, chronic hypoxia increases the expression of CXCL8 via NF-κB." (PMID 33467722, 2021). "In cancer cells, IRE1 is reported to promote immunomodulatory cytokine expression including CXCL8." (PMID 34725321, 2021). "The factors responsible for cancer cell proliferation may be a higher level of pro-inflammatory cytokines (TNF-α and CXCL8) and growth factors (VEGF, HCF, Ang-2, TGF-α, EPO, SCF, FGF, and PDGF-BB)." (PMID 34577154, 2021). "Similarly, Interleukin 8 (IL-8; CXCL8) is a chemokine with a potential cancer regulatory effect, as it is used as a biomarker in breast cancer." (PMID 33753779, 2021). "Interestingly, the same transcription factors are also emerging as key regulators for the expression of mediators such as cytokines (TNF-α), chemokines (CCL2, CXCL6, GRO, CXCL8, CXCL11), and growth factors (GM-CSF) in cancer cells." (PMID 34567000, 2021). "CXCL8 is an important regulator of the TME by promoting EMT and stemness in cancer cells." (PMID 35011369, 2021). "But in our study, we observed and generalized the significant higher mRNA expression of CXCL8 in COAD patients of different clinicopathological features including different races, cancer stages, genders, age groups, and body weights as compared to the normal controls." (PMID 34473751, 2021). "CXCL8-induced MMP-9 promotes extracellular matrix degradation, which not only provides the necessary conditions for angiogenesis, but also plays an important role in cancer cell invasion and metastasis." (PMID 32201645, 2020). "Furthermore, some studies showed IL-8 or chemokine (C-X-C motif) ligand 8 (CXCL8) receptor, C-X-C Motif Chemokine Receptor 1 (CXCR1) or CXCR2, altered CARs significantly enhance the invasion and persistence of T cells in cancer environment." (PMID 33167514, 2020). "Inhibitors of the axes of CXCL8, CCL2 and CCL5 and their receptors are also available, suggesting that treatments of TNBC cancers with combination therapies of chemokines and pro-inflammatory cytokines may provide novel treatment options for TNBC patients." (PMID 31031757, 2019). "Serum IL-8 (CXCL8) levels were significantly elevated in CRC patients and those with other cancers." (PMID 29992127, 2018). "Under in vitro conditions, they stimulated cancer cell proliferation (via IL-6), migration (via CXCL8/IL-8 and CCL2/MCP-1), and invasion (via IL-6, MMP-3 and uPA), and they triggered the EMT in a mechanism involving TGF-β1-dependent induction of Smad 2/3-Snail1 signaling." (PMID 28956065, 2018). "IL-8, also known as CXCL8, is a chemokine with a role in metastatic and advanced cancers." (PMID 30258464, 2018). "We observed various levels of CXCL8 immunoreactivities in cancer nests (negative, low and high) using corresponding normal squamous epithelia as a positive control." (PMID 29285315, 2017). "As for cancer cell migration, senescent HPMCs stimulated this process via CXCL1 and TGF-β1 (in A2780 cultures); CXCL1, CXCL8, and fibronectin in OVCAR-3 cells; and CXCL8 and IL-6 in SKOV-3 cells." (PMID 28032864, 2016). "Although CXCL8 and VCAN tend to increase in macrophages cultured with both cancer cells, statistical significance was only achieved for the anti-inflammatory marker VCAN in co-cultures with SW1463 and for the pro-inflammatory marker CXCL8 marker in co-cultures with RKO cells." (PMID 27513864, 2016). "Increased cancer cell migration was suppressed by the inhibition of CCL2 and CXCL8." (PMID 26284488, 2015). "Cixutumumab treatment stimulates STAT3-dependent transcriptional upregulation of IGF-2 in cancer cells and recruitment of macrophages and fibroblasts via paracrine IGF-2/IGF-2R activation, resulting in the stroma-derived CXCL8 production, and thus angiogenic and metastatic environment." (PMID 26465273, 2015).
cancer (continued). "IL-8 (CXCL8) is involved in a variety of physiopathological processes and along with other members of TNF superfamily were shown to be involved in the proliferation, invasion and metastasis of several cancer including colon cancer." (PMID 25408728, 2014). "Research into the role of CXCL8 in cancer has been hampered by the lack of a homologous gene in the mouse, the common animal model for studies of human cancer, and by the functional overlap between various chemokines." (PMID 24224100, 2013). "Similarly, CXCL8 activates the classical MAPK signaling cascade, with downstream phosphorylation of Erk1/2 in neutrophils and cancer cells." (PMID 24224100, 2013). "Furthermore, the chemokine receptors for CXCL8: CXCR1 and CXCR2 are expressed in human gastric carcinoma cells and play a role in the proliferation of the cancer cells." (PMID 24259307, 2013). "Nevertheless, paracrine CXCL8 growth signals on nonsenescent cancer cells or angiogenic signals on endothelial cells may indeed contribute to the poorer outcome of CALB1-negative tumors." (PMID 37192000, 2023). "Moreover, phenformin, at non-cytotoxic concentrations, had also an indirect anti-cancer effect through modulation of the chemokine milieu within the thyroid tumor microenvironment (inhibition of CXCL8 secretion)." (PMID 38146457, 2023). "Moreover, expression of CALB1 in cancer cells exhibited a highly significant inverse correlation with cancer cell–intrinsic expression of CXCL1, CXCL2, and CXCL8 and a positive correlation with CCL26 expression, which did not, however, reach statistical significance (P = 0.057)." (PMID 37192000, 2023). "Inflammatory stimulants (e.g., CXCL1, CXCL2 and CXCL8) can stimulate neutrophil chemotaxis and activation to generate chromatin webs, thereby inducing NET formation in the omentum, a preferential metastasis site of ovarian cancer, while inhibition of NETs decreased the implantation of cancer cells." (PMID 37198402, 2023). "CXCL8 and LAPTM5 proteins have been reported to promote cell activity, TMEM156 and LGALS1 proteins enhance cell invasion, VIM and LGALS1 proteins induce cell migration, FABP5 and SRGN proteins activate cancer metastasis, and the DEFB4A protein regulates immunity in human cancers." (PMID 35632763, 2022). "It has also been found that PFKFB3 promotes the interleukin-8 coding gene CXCL8 by activating the PI3K/AKT/NFκB p65 pathway, which leads to the idea that PFKFB3 inhibition might be effective in overcoming trastuzumab resistance in HER2-positive cancers." (PMID 36143438, 2022). "In addition to the C3, for these genes (CXCL8, CX3CR1, GRM8, HTR1B, HTR1D, PTGER3, SSTR1 and SUCNR1) were related to survival in the ACC and it was also could be useful in other cancers 24-31." (PMID 34220331, 2021). "In addition to these chemokine receptors, chemokine ligands such as CXCL1, CXCL2, CXCL5, CXCL6, CXCL8, and CXCL9 have been also significantly correlated with poor survival and metastasis in several cancers by recruiting MDSCs and suppressing the antitumoral activity of CD8+ T effectors cells." (PMID 32719800, 2020). "However, the chemokines and their receptors that particularly stimulate tumorigenesis, including CCR7, CXCL1, CXCL8, and CXCL12/CXCR4, could, consequently, act as poor prognostic markers for cancer patients." (PMID 31991604, 2020). "Additionally, these junctions can be destabilized by the expressions of cytokines, chemokines, and inflammatory mediators, including VEGF, basic FGF (bFGF), TGF-ß, IL-1ß, TNF-α, interferon-γ (IFN-γ), CCL2, CXCL8, and prostaglandin-endoperoxide synthase 2 (COX2), by the cancer cells." (PMID 31900168, 2020). "* Via physical contacts with cancer cells and through secreted factors, theyincreased CSC proportions, as well as EMT and migration.* The activities of the myeloid cells were mediated by or connected to solublefactors such as TNFα, IL-6 and ELR+ CXC chemokines (e.g., CXCL8 and CXCL1)." (PMID 33585241, 2020).
cancer (continued). "In parallel to CXCL8, CXCL1 also contributed to stemness, but its impacts were mostly found in regulation of EMT-related processes, migration and invasion; in this respect, CXCL1 was found to act in an autocrine manner and/or to be secreted by macrophages in vicinity of the cancer cells." (PMID 33585241, 2020). "Therefore, we used ELISA for a subset of leukocyte chemokines ‐ CXCL8 (neutrophils), CCL2 (monocytes) and CCL5 (T‐cells) to determine whether cancer cells or NTF were the main chemokine producers." (PMID 30191960, 2019). "In conclusion, these data suggest that the coexpression of CXCL8 and MMP9 could be an early detection marker for PNI, with a potential to be utilized as individual therapy targets for early treatment to prevent PNI-related cancer metastasis." (PMID 31681401, 2019). "In addition, pre‐incubation with anakinra resulted in a total abrogation of CXCL8 chemokine secretion (p < 0.001) in response to conditioned medium derived from SCC89 cancer cells for all NTF tested that was not evident in the placebo control." (PMID 30191960, 2019). "Therefore, our data suggested that the activation of PI3K and its downstream effector AKT by CUL1-induced CXCL8 and IL11 may play a role in cancer metastasis." (PMID 30578411, 2018). "CXCL8 is a proinflammatory chemokine that acts on leukocytes and endothelial cells, via their CXCR1 and CXCR2 receptors, to promote immune infiltration and angiogenesis, which in turn establishes a venue for cancer cell local invasion, migration, and metastasis." (PMID 24224100, 2013). "Regarding the role of CXCL8, a question is whether or not primary cancer cells and their metastatic derivatives differ in their expression and secretion of CXCL8." (PMID 24224100, 2013). "Thus, an attractive hypothesis is that increased epithelial IGF-2 production leads to macrophage and fibroblast chemotaxis, which subsequently stimulates CXCL8 expression in stromal cells through the IG-F2/IGF-2R axis, resulting in endothelial cell recruitment and cancer cell migration." (PMID 26465273, 2015). "In biopsies lacking CALB1 expression, cancer cells not only transcribed CXCL1, CXCL2, CXCL8, and other immune mediators; they were also the predominant source." (PMID 37192000, 2023). "In the context of CRC, both hypoxic and fusobacterium nucleatum infected cancer cells can secret CXCL8 which subsequently contribute to the EMT of normoxic and noninfected cancer cells." (PMID 35372515, 2022). "Although the mechanism of IL-8 (CXCL8) mediated M-MDSC expansion is not established, IL-8 facilitates differentiation and subsequent mobilization of MDSC in patients diagnosed with several types of cancers." (PMID 35812392, 2022). "Our datasets suggest that in response to MIT‐mediated chemotherapy, cancer cells also become senescent, but they do not express a typical SASP, as the expression levels of a number of key SASP factors such as IL1α, IL6, CXCL8, and MMP1 remained largely unchanged." (PMID 40265973, 2025). "Additionally, an analysis of COAD and adjacent non-cancerous tissue samples from the TCGA database confirmed significant increases in CXCL1, CXCL8, CXCL9, and CXCL11 in cancer tissues, while CCL22 showed no significant change." (PMID 38791448, 2024). "Many previous studies have already demonstrated its up-regulation in CRC patients relative to controls, however, none of these studies generalized CXCL8 in CRC patients of different clinicopathological features (different races, cancer stages, genders, age groups, and body weights)." (PMID 34473751, 2021). "CXCL8 is one of the inflammatory ELR (+) chemokines, which is not only a critical regulator of normal CNS function and development, but plays an important role in many CNS disorders, including malignant tumors." (PMID 32456359, 2020).
cancer (continued). "We studied therefore the expression of two relatively less well-studied chemokines CXCL6 and CXCL4 along with the better-studied CXCL8 (IL-8) and VEGF in both carcinoma and adjacent noncancerous tissue and correlated with several cancer indices, trophic factors, and patient survival." (PMID 29850390, 2018).